TLR4 (toll like receptor 4)
Diseases named in the same sentence as TLR4 in open-access papers (continued):
Sharing a sentence is not in itself a finding about the gene and the disease.
colitis (continued). "Consistent with our proposal, paeonol was reported to alleviate C. albicans-associated colitis induced by DSS in mice through suppressing dectin-1/NF-κB signaling in combination with TLR2 and TLR4, while the antifungal drug fluconazole treatment could rescue the ulcerative colitis symptoms in mice." (PMID 37540386, 2023). "However, TLR4 ameliorated colitis by upregulating Treg cells by interacting with A. muciniphila." (PMID 37191444, 2023). "Herein, the DSS-induced colitis in mice was established to explore the protective effects and related mechanisms of glycated caseinate, focusing on alterations in the biochemical markers from serum and colon, and the expression of key proteins involved in the TLR4/NF-κB signaling pathway." (PMID 37761139, 2023). "Nec-1, RIP3, inhibitor has a therapeutic effect on colitis mice via promoting ZO-1 expression and the proportion of Treg cells, and alleviating the secretion of inflammatory cytokines and necroptosis of mouse intestinal epithelial cells by inhibiting TLR4/MyD88/NF-κB and ROS generation." (PMID 35346043, 2022). "The therapeutic effect of SSP on colitis with SKYD syndromes might be related to the inhibition of the TLR4/NF-κB signaling pathway, which corrects the immune interactions of GM or microflora metabolites with infDCs, and then maintains the symbiotic relationship between the microflora and the host." (PMID 36310616, 2022). "Thus, we hypothesize that elevation of TDAG51 negatively regulates PPARγ activity or PPARγ expression per se in DSS-induced colitis model mice, thereby possibly promoting the production of inflammatory mediators via the TLR4/NF-κB signaling pathway." (PMID 36450854, 2022). "Furthermore, our previous study also demonstrated that arabinogalactan-type LBP-3 exhibited an ameliorative effect against DSS-induced colitis by inhibiting the activation of TLR4-MyD88-NF-κB signaling pathways and reshaping the gut microbiota, as well as improving SCFA generation." (PMID 37430929, 2022). "Therefore, Kae may exert protective effects against colitis mice through regulating the gut microbiota and TLR4-related signaling pathways." (PMID 34367139, 2021). "In vitro, soyasaponin Ab administration to TLR4 siRNA-treated peritoneal macrophages did not affect TLR4 expression or LPS-induced NF-κB activation, suggesting that soyasaponin may ameliorate colitis through the inhibition of LPS binding to TLR4 on macrophages." (PMID 33916612, 2021). "It was speculated that Q7-EVs improved colitis by regulating the TLR4-MyD88-NF-κB pathway." (PMID 34925349, 2021). "In contrast, several strategies based on TLR4 blocking show promising results in the context of epithelial restoration in IBD (not in the case of necrotizing enterocolitis), while constitutively activated TLR4 predisposes for DSS-colitis and colitis-induced neoplasia." (PMID 34368179, 2021). "Therefore, IAP protects against colitis by reducing TLR4 pathways activation." (PMID 33494775, 2021). "We propose Sanhuang decoction enema may function as an effective anti-UC approach by reducing the additional impact of C. albicans on the progression of DSS-induced colitis, decreasing fecal fungal burden and lowering systemic inflammation mainly via the TLR4/NF-kB and PI3K-Akt pathways." (PMID 34376226, 2021). "Furthermore, Luo and colleagues provided evidence that baicalin attenuated colitis induced by trinitro-benzene-sulfonic acid (TNBS) via inhibiting the toll like receptor-4 (TLR4)/myeloid differential protein-88 (MyD88) signaling cascade and inactivating the NOD-like receptor 3 (NLRP3) inflammasome." (PMID 32988394, 2020). "Moreover, IAP reduced the severity of DSS-induced colitis in mice in a TLR4-dependent manner." (PMID 32080230, 2020).
colitis (continued). "Thus, we speculated that MRS may exert a protective effect in acetic acid-induced colitis via the TLR-4/NF-κB/MAPK signaling pathway." (PMID 31182999, 2019). "Moreover, oral administration of ginsenoside Rg1 as a representative component belonging to protopanaxatriol saponins in RGE was reported to ameliorate TNBS-induced colitis by inhibiting the binding of lipopolysaccharide (LPS) to TLR4 on macrophages and by restoring Th17/Treg balance." (PMID 28828029, 2017). "This prompted us to study gastrointestinal colonization properties and potential TLR4 dependent intestinal as well as extra-intestinal immune responses upon MDR PA challenge under chronic intestinal inflammatory conditions applying the chronic IL10−/− colitis mouse model." (PMID 29151895, 2017). "However, a mouse model of colitis has demonstrated that lactic acid bacteria may improve colitis via inhibition of TLR4- mediated NF-κB activation." (PMID 22970150, 2012). "Therefore the continuous overdrive of the epithelial TLR4-COX-2-PGE2 axis during the chronic phase of colitis may be the key factor in the pathogenesis of CAC." (PMID 24212947, 2011). "However, sustained activation of this TLR4-COX-2-PGE2 axis may result in aberrant epithelial cell proliferation and thus lead to colitis-associated tumor development." (PMID 24212947, 2011). "In TLR4-deficient mice, neither AR nor epiregulin is expressed following mucosal injury, which is consistent with their phenotype, which includes a defective recovery from colitis." (PMID 24212947, 2011). "In addition, the colitis and colitis-associated colorectal tumors (CAC) spontaneously generated in IL10−/− mice can be ameliorated if mice are kept in germ-free conditions or concurrently ablated of TLR4." (PMID 20885960, 2010). "Moreover, deletion of TLR4 rescued the colitis in these TLR5 knockout mice." (PMID 21203467, 2010). "As expected, the induction of acute colitis resulted in elevated levels of proinflammatory mediators such as TNF-α, PTX3, and PAF in plasma and TLR4 in colon tissue." (PMID 40572721, 2025). "For instance, cathepsin K (CTSK) from the microbiota can induce TLR4-dependent anti-inflammatory macrophages, and SCFA-producing bacteria collectively suppress JAK/STAT3/FOXO3 signaling to ameliorate colitis." (PMID 41150761, 2025). "Prior studies highlight Eng’s therapeutic potential in colitis models, including its ability to attenuate TNBS-induced Crohn’s-like colitis via TLR4/NF-κB pathway inhibition." (PMID 40427406, 2025). "Our findings demonstrate that Indoximod significantly reduced colonic TLR4 expression and plasma levels of TNF-α and PTX3 while also improving histopathological damage in rats with acetic acid-induced colitis." (PMID 40572721, 2025). "Reduced hepatocyte swelling in mice with colitis, inhibited IL-1β and TNF-α expression, and attenuated hepatic inflammation and cholestasis by regulating TLR4 NF-κB and bile acid metabolic pathways." (PMID 40066456, 2025). "HEK-Blue mTLR4 cells, a TLR4 reporter cell line that secretes alkaline phosphatase after TLR4 activation via the NF-κB signaling pathway, were treated with plasma of the 4-HNE-treated murine colitis model." (PMID 40489926, 2025). "In summary, andrographolide sulfonates exert potent anti-inflammatory effects in colitis by targeting multiple pathways, including YAP, TLR4/MyD88/NF-κB, and p38 signaling." (PMID 40005997, 2025). "Research indicated that TLR4 overexpression aggravated inflammation and intestinal injury in DSS-induced colitis models." (PMID 40756994, 2025). "In conclusion, OP treatment can inhibit the TLR4/NF-κB pathway and improve the intestinal microbiota in UC mice, which in turn alleviates DSS-induced colitis, providing a reference for the treatment of clinical UC patients." (PMID 38892524, 2024).
colitis (continued). "In addition, Toll-like receptor 4 (TLR4), one of the upstream signaling pathways of NF-kB, was blocked by RA administration to reduce inflammation via a competitive interaction with TLR4 at the binding sites of Arg-264 residue in a disease-related colitis mouse model." (PMID 38731431, 2024). "The mRNA levels of TLR4, MyD88, and NF-ĸB in the DSS-induced colitis group of this study were significantly higher than the normal control group." (PMID 39323474, 2024). "Garlic-derived miRNA (Han-miR3630-5p) can bind to and inhibit toll-like receptor 4 (TLR4), thus alleviating DSS-induced colitis." (PMID 39741676, 2024). "CPP1-2-1, on the other hand, reduces the expression of TLR4, NF-κB, TNF-α, and IL-6 in LPS-induced RAW264.7 cells in a dose-dependent manner and alleviates DSS-induced pathological injury in mice with colitis." (PMID 39202931, 2024). "Both TLR-4 lps−/lps- and WT mice treatments with L. casei showed a significant reduction in the clinical and histopathological manifestations of DSS colitis." (PMID 39323474, 2024). "We have reported that CM1 exerts an anti-inflammatory effect on TLR4-stimulated primary dendritic cells and mice with DSS-induced colitis and has therapeutic potential for inflammatory bowel disease." (PMID 38474770, 2024). "Naringenin was reported to significantly improve colitis in dextran sulfate sodium (DSS)-induced UC in mice by impeding NF-κB and TLR4 protein activity." (PMID 37895902, 2023). "In conclusion, EA at Zusanli (ST36) relieved hyperalgesia induced by colitis via the inhibition of surface neurogenic inflammation and sympathetic sprouting into the DRG, which were mediated by TRPV1/CGRP, ERK, and TLR4 signaling pathway deactivation." (PMID 36910013, 2023). "Damage-associated molecular patterns S100A8 and S100A9 play an important role in colitis by binding to their pattern recognition receptors PRR, especially TLR4." (PMID 38273841, 2023). "In terms of mechanism, PHI inhibited the phosphorylation of tyrosine kinase Src mediated by TLR4, and then reduced the activation of its downstream pathway involving p38, JNK, and NF-κB, thereby reducing intestinal inflammation of colitis mice." (PMID 36768559, 2023). "Previous studies have shown that interferon-γ and TNFα induce TLR4 transcription, which in turn is required for the induction of cyclooxygenase 2 expression in DSS-induced colitis in mice." (PMID 36768553, 2023). "In this study, the results from Western blot assays suggested that higher levels of TLR4, NF-κB p65, IKB-α and MyD88 were detected in the DSS-induced colitis compared to the control group." (PMID 37761139, 2023). "Western blotting displayed that the PHI inhibited the activation of tyrosine kinase Src mediated by TLR4, and then reduced the phosphorylation of downstream proteins p38, JNK, and NF-κB in colitis mice." (PMID 36768559, 2023). "QA ameliorated UC through the inhibition of two TLR4‐NF‐κB and NF‐κB‐INOS‐NO signaling pathways, which results in the reduction of colitis complications, including oxidative stress, inflammation, apoptosis and histopathological injuries in rats." (PMID 37647443, 2023). "It has been well established that TLR4 and the downstream binding protein of MyD88 facilitate DSS-induced colitis by activating NF-kB to promote the transcription of inflammation genes." (PMID 37761139, 2023). "Similar to those results of LPS stimulated-RAW264.7 cells, PHI (100mg/kg) treatment significantly reduced the expression level of TLR4 protein and the phosphorylation levels of Src, p65, IκBα, p38, and JNK proteins in colon tissues of colitis mice (P < 0.05)." (PMID 36768559, 2023). "This is in line with previous studies that the TLR-4 expression and NF-κB activation are greatly upregulated in the colonic tissues of patients with IBD and mice with DSS-induced colitis." (PMID 36176442, 2022).
colitis (continued). "Our results demonstrated that melatonin-mediated MT2 inhibits Aeromonas-goblet cell interactions to restore the level of MUC2 production via LPS/TLR4/MyD88/GSK-3β/ROS/NF-κB loop, further improving colitis in SD mice." (PMID 35355860, 2022). "It seems that boosting LPS activates the TLR4-MyD88-GSK-3β-NF-κB pathway and promotes MUC2 depletion, further inducing colitis." (PMID 35355860, 2022). "Coinciding with the results of the current study, the crosstalk between TLR4, NLRP3 inflammasome, and NF-κB signaling was proven to be a key regulator of the pathophysiology of DSS-induced colitis." (PMID 35631426, 2022). "Our consequences displayed that anethole considerably decreased the level of MDA, increased the TAC, and decreased the gene expression of inflammatory cytokines including TLR4, TNF-α and IL-1β in the colon tissue of the colitis group." (PMID 35432569, 2022). "In our study, DSS increased the protein levels of TLR-4 and NF-κB p65 in the colon, suggesting that DSS activates the TLR-4/NF-κB pathway and results in a pro-inflammatory response in DSS-induced colitis mice." (PMID 36176442, 2022). "Second, this is the first report, to our knowledge, showing that macrophage-specific eNAMPT functions as a protective factor to alleviate the severity of colitis through inhibiting the binding by macrophages of CYBB and TLR4 to circulating eNAMPT." (PMID 36552583, 2022). "Overall, our study revealed that MT2-mediated MT suppressed Aeromonas coupling with goblet cells and restored MUC2 depletion by inhibiting the TLR4/MyD88/GSK-3β/β-catenin/ROS/NF-κB loop, ultimately improving SD-induced colitis in mice." (PMID 35355860, 2022). "Luteolin also relieved DSS-induced colitis in mice, and the mechanism by which is due to the suppression of high mobility group box chromosomal 1 (HMGB1), TLR4, and NF-κB p65 protein levels in the colon." (PMID 35805952, 2022). "TLR4 has been suggested as an intermediary between NF-κB and Nrf2, and Maresin-1 (pro-resolving lipid synthesized in macrophages) reduced TLR4/NF-κB mechanism and activated Nrf2 in DSS-induced colitis mice." (PMID 35277165, 2022). "Our data suggest that pretreatment with Rg1 and ADSC + Rg1 markedly decreases the levels of TLR4 and MyD88, as well as the expression of TNF-α, IL-6, IL-1β, IFN-γ, and IL-17A in the DSS-induced mouse model of colitis." (PMID 35729638, 2022). "A recent study showed that Tlr4-, Tlr2-, or Myd88-knockout mice exposed to dextran sulfate sodium (DSS) show more severe colitis than wildtype mice." (PMID 34075172, 2021). "The results showed that oral Q7-EVs down-regulated TLR4 and MyD88 gene expression compared with DSS-induced colitis mice." (PMID 34925349, 2021). "To conclude, oral administration of mEVs attenuated intestinal inflammation via inhibiting TLR4-NF-κB and NLRP3 signaling pathways, restoring Treg/Th17 cell balance and the gut microbiota, thus prevented disease progression of colitis." (PMID 34373759, 2021). "First, we observed a strong increase in Tlr4 expression in the colon of mice during the inflammatory phases of AOM/DSS treatment, which points towards an involvement of TLR4 in colitis induction." (PMID 34025672, 2021). "Naturally, the effects of curcumin on the regulation of TLRs signaling pathways in colitis mice were further investigated by Western blot analysis, including TLRs signaling molecules TLR2 and TLR4 and the downstream proteins MyD88, NF-κBp65, p38MAPK, and AP-1." (PMID 34567209, 2021). "Consequently, CNQX can inhibit the intestinal inflammatory response in mice with colitis, inhibit the mucosal barrier injury, increase the expression of tight junction proteins (including occludin and claudin‐1) and decrease the expression levels of MyD88, TLR4 and MD2." (PMID 34184406, 2021).
colitis (continued). "GQD oral administration was found to alleviate the severity of colitis in DSS-induced mice model, with reduced toll-like receptor 4 expression and NF-κB activation, as well as decreased level of pro-inflammatory cytokines." (PMID 34059101, 2021). "Targeted inhibition of MD-1 stimulates the TLR4/MyD88/NF-κB signaling axis in colitis-induced mice, which also proves the role of RP105 as a TLR4 inhibitor." (PMID 34414191, 2021). "Consistently, seminal work from Medzhitov's lab showed the crucial role of TLR4/MyD88 signaling for the maintenance of the intestinal homeostasis and barrier repair during acute DSS colitis in microbiota dependent manner." (PMID 34124086, 2021). "It was further demonstrated that the amelioration of dextran sulfate sodium-induced colitis by EcN is mediated via TLR-2- and TLR-4-dependent pathways." (PMID 33679699, 2020). "This study showed that expression of TLR2, TLR4, TLR9, and MyD88 mRNA was significantly increased in colonic tissues of DSS-induced colitis mice relative to the normal control mice." (PMID 33193406, 2020). "Protein expression of both TLR4 and MyD88 was significantly elevated in colonic tissues of DSS-induced colitis mice compared to the normal control mice by Western blotting." (PMID 33193406, 2020). "Recent data pointed that TLR4-knockout mice showed a less inflammatory infiltration and a decreased expression of TRPV1 in TNBS-induced colitis, indicating one possible function of TLR4 for mediating TRPV1 signaling under inflammatory conditions." (PMID 32153564, 2020). "In one TNBS-colitis model, n-3-PUFA was found to increase TLR-2 and IL-1A gene expression in rat colon tissue, whereas n-9 increased TLR-4 expression." (PMID 33603741, 2020). "In fact, inhibition in the production of TLR-4, NF-κB p65, COX-2, IL-17, TNF-α, IL-1β, and IL-6 is considered useful in treating colitis." (PMID 32848723, 2020). "In our results, we demonstrated that repeated EA intervention ameliorates DSS-induced colitis by suppressing proinflammatory mediators, including CRP, IFN-γ, TNF-α, and IL-6 through the TLR4 signaling via MyD88-dependent pathway." (PMID 32419794, 2020). "Compared with the DSS-induced colitis group, the groups treated with TAK-242 had significantly downregulated expression of TLR4." (PMID 32762699, 2020). "In our data, pinocembrin remarkably suppressed the mRNA expression of TLR4, Myd88, iNOS, COX-2 and TNF-α, as well as the increased protein expression of TLR4 and phosphorylated NF-κB p65 in the colon of DSS colitis mice." (PMID 32687156, 2020). "In conclusion, QCWZD can protect against DSS-induced colitis by modulating gut microbiota and promoting NLRP12 expression, which occurs via the inhibition of the activity of the TLR4/Blimp-1 axis." (PMID 31061672, 2019). "TLR-4 and TLR-8 expression increased significantly in response to both C. albicans overgrowth and colitis while treatment with DHMB decreased the expression of these receptors in the colons." (PMID 30646601, 2019). "COX-2 expression is closely related to TLR4/NF-κB pathway in the intestine, particularly in the setting of DSS colitis." (PMID 30013563, 2018). "In colitis groups, n-3 diet upregulated IL-1A, TLR-2, and MA2K3 genes while n-9 diet upregulated TLR-4 genes (P = 0.044, P = 0.013, and P = 0.021, resp.)." (PMID 29670469, 2018). "TLR4/NF-κB and IL-6/JAK2/STAT3 signal pathways were investigated to evaluate the alleviation of CP on the TNBS-induced colitis." (PMID 30042683, 2018). "In colitic models, exogenous administration of IAP improved the macroscopically and microscopically finding of colonic inflammation through inhibition of LPS-induced production of TNF-α and IL-6 and TLR-4 dependent pathway." (PMID 30558547, 2018). "TLR4 is generally expressed at low level in the intestinal mucosa but is notably up-regulated in IBD patients and colitis rats which implied its important role in the pathogenesis of IBD." (PMID 30042683, 2018).